CD14 (CD14 molecule)
Diseases named in the same sentence as CD14 in open-access papers (continued):
Sharing a sentence is not in itself a finding about the gene and the disease.
glioma (continued). "The subsequent correlation analyses also indicated MD2 was strongly correlated with CD14, LY86, TLR1 and TLR4 in gliomas." (PMID 35372062, 2022). "Microglia in IDH1-mut gliomas expressed similar levels of HLA-DR as microglia in IDH1-wt gliomas and BrM; however, only in IDH1-wt gliomas did these cells upregulate CD14 and CD64, which is a sign of their activation." (PMID 33809675, 2021). "In line with previous observations of three other studies in pancreatic epithelial cell lines and glioma, our subcellular localization analysis demonstrated that PSMB8-AS1 is present in the cytoplasm of CD14+ monocytes." (PMID 33922041, 2021). "In 63 adult patients with gliomas and 31 healthy controls, the expressions of TREM-1 and TREM-2 on CD14+ blood cells (method: flow cytometry) and the levels of soluble sTREM-1, HMGB1, IL-6, and IL-10 (Elisa tests) were analyzed." (PMID 32684831, 2020). "We also performed immunohistochemical staining of immune cell-specific markers including CD11b, CD14, CD56, CD11c, FOXP3, CD8 and CD4 in glioma tissues." (PMID 31377744, 2019). "Several molecules have been reported as specific markers of TAMs in glioma, including CD204, CD163, CD11b, CD14, and CD68." (PMID 31140757, 2019). "Collectively, these results indicate that the increase in CD14+ monocytes in glioma patients is not due to dexamethasone and suggest a dysregulation of the myeloid compartment." (PMID 35069595, 2021). "To determine whether our findings are clinically relevant, we stained glioma tissue sections (n = 50) for BATF2, SDF-1α, HIF-1α (hypoxia marker), CD14 (Mo-MDSCs marker), and CD33 (MDSCs marker)." (PMID 33452462, 2021). "We found a negative correlation of the serum levels of HMGB1 in glioma patients with both percentages of CD14+ TREM-1+ cells (P = 0.049) and TREM-1/TREM-2 ratio (P = 0.004)." (PMID 32684831, 2020). "The difference in the percentage of CD14+ Mo between all groups of glioma patients and healthy controls was not statistically significant." (PMID 32684831, 2020). "Our studies detected five proteins that interacted with Fstl1 in glioma using Co-IP and pulldown experiments, i.e., DIP2A, CD14, BMP4, ActR-IIB, and follistatin, and the mRNA levels of MGMT were only increased in GBM cells transfected with DIP2A-specific siRNA (siDIP2A)." (PMID 30542120, 2019). "Therefore, we assessed the expression of the different Siglec family members on sorted M-MDSCs (CD33+ MHC IIlow/− CD14+) and PMN-MDSCs (CD33+ MHC IIlow/− CD15+) from the blood of glioma patients." (PMID 30953118, 2019). "The reason for the reduced VNN2 expression in the biological response of M-MDSCs to gliomas has not yet been investigated, but the detection of CD14+/VNN2high MDSCs in peripheral blood is considered an additional useful marker in the diagnostic spectrum of tumor diagnosis." (PMID 38275375, 2023). "In the current study, the three monocyte subpopulations: classical (CD14+ CD16+ SLAN−), intermediate (CD14dim CD16+ SLAN−) and non-classical (CD14low/− CD16+ SLAN+) in glioma patients’ peripheral blood were analysed with flow cytometry." (PMID 36768201, 2023).
dengue (35 papers, 2008 to 2025). "For example, Dengue virus infection induces CD14+CD16+ monocyte differentiation, which can stimulate plasmablast B-cell differentiation and IgG/IgM secretion." (PMID 39656009, 2025). "Altogether, these results indicate that TLR2/TLR6/CD14- mediated sensing of immature dengue particles induces the production of TNF-α and IL-1β by monocytes." (PMID 36240261, 2022). "A previous study reported a reduced number of CD14(+) human leukocyte antigen (HLA)-DR (+) monocytes in patients with severe dengue compared to those with mild dengue and controls." (PMID 34603272, 2021). "All the NHP monocyte subsets explicitly express CD14, therefore, we used the same surface marker to identify circulating monocytes in rhesus macaques in the dengue vaccinated group." (PMID 33732548, 2021). "In parallel, the percentage of CD19+NS3+ B cells in dengue patients was significantly lower compared to CD14+NS3+ monocytes (20.9 vs 56.5%; p < 0.05)." (PMID 33643283, 2020). "in which frequencies of CD14++CD16+ intermediate monocytes positively correlated with concentrations of BAFF in blood of dengue patients." (PMID 33643283, 2020). "CD14+ monocytes were the major contributors of IL-10 transcript further confirming the role of monocytes in the pathogenesis of dengue disease." (PMID 26982706, 2016). "Recent evidence suggests that cytokines produced by CD14+CD16+ monocytes contribute to plasmablast formation in dengue patients." (PMID 25177321, 2014). "In vivo, CD14+ monocytes in the blood of acute dengue patients contained significantly higher levels of DENV genomic RNA in severe DHF compared to DF cases, and in secondary compared to 1° infections." (PMID 25566258, 2014). "We evaluated NO, NS1 serum levels (ELISA), TNF-α production by peripheral blood mononuclear cells (PBMCs), and TLR4 expression on CD14+ cells from 37 dengue patients and 20 healthy controls." (PMID 25580138, 2014). "CD14+CD16+ monocytes may help neutralize Dengue virus infection but enhance disease upon infection with another, secondary serotype, Dengue virus." (PMID 39656009, 2025). "In a previous study, a differentially expressed TLR profile was reported in children with severe dengue, wherein increased expression of TLR7 and TLR4 transcript variant 3 (TLR4R3) and decreased expression of TLR1, TLR2, TLR4R4, and TLR4 cofactor CD14 were observed." (PMID 34603272, 2021). "We questioned whether ITM and/or NC subset expansion in dengue virus infection was merely due to a modulation in CD14 and/or CD16 expression on some monocytes, or a true expansion of the subset(s)." (PMID 31402918, 2019). "Similarly, DENV infection also showed elevated frequencies of intermediate monocytes, though to a lesser extent, in line with a previous report showing expansion of CD14+CD16+ monocytes during acute dengue and their role in promoting plasma blast differentiation and anti-DENV antibody responses." (PMID 41346606, 2025). "However, body fat index was higher in obese individuals who had recent inapparent dengue (14.7 ± 3.1 versus 12.7 ± 2.1 kg/m2, p = 0.04), as was the expression of CD11b by classical (CD14++CD16−) monocytes (1103.0 ± 311.3 versus 720.3 ± 281.1 mean fluoresce intensity)." (PMID 36680274, 2023). "The expansion of non-classical CD14+CD16+ monocytes has shown to associate with severe dengue." (PMID 33194836, 2020). "DENV infection induced expansion of CD16+ intermediate monocytes (CD14+CD16+), both in vitro and as reflected in human Dengue patient single-cell data." (PMID 41012666, 2025). "Single-cell transcriptomics demonstrated a progressive increase in intermediate monocytes (CD14++/FCGR3A+) across clinical severity groups, peaking in severe Dengue." (PMID 41012666, 2025). "IFITI and CD163 expression in CD14+CD16+ monocytes, was shown to precede the development of severe dengue." (PMID 33194836, 2020).
dengue (continued). "Similar to our findings, another study that analyzed blood samples from a Sri Lankan cohort of dengue fever and DHF cases found a decrease in CD14+ and CD14dim monocytes, in line with our findings." (PMID 29079750, 2017). "To further confirm the contribution of monocytes in secreting inflammatory mediators in dengue infection we performed bulk sorting of PBMCs from two dengue patients and isolated CD3+, CD19+, CD14+ and CD16+ cells." (PMID 26982706, 2016). "Recent studies have confirmed the involvement of CD14 in antiviral immunity to control HIV, respiratory syncytial virus, and dengue virus infection." (PMID 28096567, 2016). "CD14+ monocytes expressing TLR2 were reported by Azeredo and colleagues (2010) to be increased in peripheral blood of dengue patients." (PMID 26226614, 2015). "Upon dengue virus infection, higher percentages of TLR6+CD14+ cell population was observed compared to the mock-infected PBMC on day 2 and 3 post-infection." (PMID 26226614, 2015). "Similar to our findings after secondary infection, this analysis revealed two classical (CD14+CD16−), two intermediate (CD14+CD16low) and one non-classical (CD14+CD16high) monocyte sub-population in the blood of primary dengue cases." (PMID 37055751, 2023). "Within the innate cell compartment, FlowSOM clustering of gated CD14+ monocytes revealed two classical (CD14+CD16−), two intermediate (CD14+CD16low) and one non-classical (CD14+CD16high) monocyte sub-population in the blood of dengue patients." (PMID 37055751, 2023). "Our first priority was to compare the levels of IL-1b, IL-2, IL-4, IL-6, IL-8, IL-10, IL-12p70, IL-17A, IL-33, CD14, CD54, CD62E, CD62L, CD62p, CD106, CD121b, CD154, CD178, GM-CSF, IFN-g, MIF, ST2 and TNF in plasma samples of dengue group, OF group and Healthy group." (PMID 33809042, 2021). "In addition, CD14(+) monocytes expressing TLR2 and TLR4 were increased in peripheral blood from mild dengue patients compared to in that of patients with severe dengue, suggesting the protective role of TLR2 and TLR4 in this setting." (PMID 34603272, 2021). "CD19+ B cells and CD14+ monocytes isolated from healthy donors were infected with either of a laboratory reference strains DENV1 Hawaii, DENV2 New Guinea C or low passaged DENV-1 and -2 isolated from acute dengue patients." (PMID 33643283, 2020). "We then applied our marker combination to assess whether the expansion of a monocyte subset in acute dengue virus infection is real, or the result of differential CD16 and/or CD14 marker expression." (PMID 31402918, 2019). "Sorting of monocytes from dengue patient peripheral blood mononuclear cells revealed that it is the CD14+ cells, but not the CD16+ or the T or B cells, that were infected with dengue virus and were major producers of IL-10." (PMID 26982706, 2016). "CD14 positive monocytes were isolated from PBMC harvested from blood collected from healthy donors that were known to be IgG negative for dengue." (PMID 24130917, 2013). "In addition, weinvestigated the CXCL-10 production after in vitroIFN-γ stimulation of PBMCs from 48 DV-infected individuals(with different clinical forms of dengue fever) and 20 NI individuals usingELISA, and CD119 expression on CD14+ cells with flow cytometry." (PMID 39082520, 2024). "In earlier stages of the disease, most DENV-infected cells in the peripheral blood of acute dengue patients were identified as CD14+ CD11c+ activated monocytes, with higher proportions of monocytes and DENV-infected total cells in the blood in DHF compared to DF patients." (PMID 25566258, 2014). "We performed a longitudinal study by a detailed phenotypic comparison of classical (CD14++CD16−, non-classical (CD14+CD16++) and intermediate (CD14++CD16+) monocyte subsets in blood samples from dengue fever (DF) to the severe dengue hemorrhagic fever (DHF) and healthy individuals." (PMID 34832614, 2021).
inflammatory bowel disease (34 papers, 2012 to 2025). A spectrum of small and large bowel inflammatory diseases of unknown etiology. "Cd14 and Alpk1 both encode pathogen recognition receptors and are known candidate genes for affecting severity in inflammatory bowel diseases." (PMID 32076438, 2020). "Polymorphisms of CD14 have been widely studied in inflammatory bowel disease and results showed a varied susceptibility in different populations, indicating that genotype frequencies vary between the populations." (PMID 28122493, 2017). "CD14 has been shown to protect against experimentally induced inflammatory bowel disease via sustaining intestinal integrity and barrier function." (PMID 39287375, 2024). "The agonist INT-747, a Farnesoid X receptor agonist, significantly reduces TNF-α secretion in activated human peripheral blood monocytes, purified CD14 monocytes and DCs, and monocytes from the lamina propria of inflammatory bowel disease (IBD) patients." (PMID 38903520, 2024). "In particular, Monocyte CD14+ primary cells play a dominant role in Alzheimer, Crohn’s disease, inflammatory bowel disease and ulcerative colitis." (PMID 36744920, 2023). "Previous reports showed beneficial effects of CD14 against inflammatory bowel disease by mitigating inflammation and enhancing intestinal barrier function." (PMID 34646849, 2021). "CD14 is a membrane protein that is constitutively expressed on the surfaces of epithelial cells and showed beneficial effects against inflammatory bowel disease by mitigating inflammation and enhancing intestinal barrier function." (PMID 34646849, 2021). "Macrophages with a cell surface phenotype of CD11cHiCCR2+CX3CR1+ are found in the intestinal wall of subjects with inflammatory bowel disease and are thought to be derived from CD14+ monocytes." (PMID 32544188, 2020). "Ephrin receptor signaling, upregulated in sarcoidosis CD14 monocytes, has been an attractive therapeutic target for both infection and cancer and has recently been investigated as a therapy for Inflammatory Bowel Disease." (PMID 33363531, 2020). "Population stratification is potentially confounding the role of CD14 in inflammatory bowel disease." (PMID 23730203, 2012). "Similarly, cells expressing the monocyte marker CD14 accumulate in the inflamed mucosa of inflammatory bowel disease (IBD) patients and these too have a high capacity to naive stimulate T cells and generate gut tropic Th1 cells and Th17 cells." (PMID 30574151, 2018). "SP2 may contribute to the differential expression level between B6 and C3Bir mice and was identified as innovative target for the therapy of inflammatory bowel diseases supporting the upregulation of the protective CD14 protein." (PMID 27191968, 2016). "Similarly the CD14 -159C/T SNP necessitates the need for higher corticosteroid doses in individuals suffering from inflammatory bowel disease." (PMID 23730203, 2012). "Circulating CD14+CD45+ fibrocytes arise from monocyte precursors and undergo recruitment and activation in several inflammatory conditions, such as NEC, inflammatory bowel disease, and cancers." (PMID 33785826, 2021). "The selective expansion of peripheral blood CD14+CD16+ monocytes correlates with disease severity in RA, Inflammatory Bowel Disease (IBD), and psoriasis." (PMID 30357490, 2019). "Notably, an increase in CD14+, CD16+, CD11b+65, and xCT+ lamina propria myeloid cells 12 correlates with a decrease in n‐butyrate producing bacteria 66 as well as diminished mucosal n‐butyrate uptake and oxidation in inflammatory bowel disease when compared to healthy conditions." (PMID 28681454, 2017).
liver fibrosis (34 papers, 2010 to 2026). "A preliminary cohort study has revealed that CD14 and CD16 positive (CD14+/CD16+) leukocyte EVs counts in plasma are inversely associated with liver fibrosis severity and show potential to improve risk prediction of severe fibrosis in NAFLD." (PMID 37221595, 2023). "At 21 days after BDL, hepatic fibrosis was reported to be 30-50% less in CD14-deficient and in LBP-deficient mice than in the WT mice." (PMID 32373617, 2020). "This study showed that CD11b CD14+ monocytes isolated from bone marrow in association with PZQ chemotherapy seems promising to improve the effects of liver fibrosis caused in mice by chronic S. mansoni infection." (PMID 31015492, 2019). "A lower degree of liver fibrosis was documented in studies of carbon tetrachloride- or bile duct ligation-induced liver fibrosis in TLR4-mutant mice along with mutations in MyD88, CD14, TRIF and LBP." (PMID 39201329, 2024). "Another study showed that Dectin-1 also interacts with TLR4 and CD14 to alleviate liver fibrosis and oncogenesis." (PMID 39590166, 2024). "CD14+ CD16+ EVs improved the ability of liver fibrosis scores to identify patients with F3/F4 fibrosis in a small preliminary cohort." (PMID 36555854, 2022). "An inverse association has been reported between membrane proteins CD14+ and CD16+ EVs and liver fibrosis severity in NAFLD." (PMID 36293192, 2022). "The accumulation of a population of macrophages with the CD14+HLA-DRhiCD206+ phenotype that secretes GM-CSF and TNFα contributes to liver fibrosis." (PMID 33050138, 2020). "The authors suggest that the LPS produced by the intestinal flora activates CD14+HLA-DRhiCD206+ macrophages and blocking the production of GM-CSF inhibits the accumulation of the population to ameliorate liver fibrosis." (PMID 33050138, 2020). "β-Elemene decreases the levels of endotoxin in plasma, TNF-α in serum, and CD14 in the liver of rats with liver fibrosis, preventing concurrent liver fibrosis induced by carbon tetrachloride (CCl4) and reducing liver injury and inflammatory reactions." (PMID 32149121, 2020). "In an analysis of 120 HIV-monoinfected, HCV-monoinfected, and HIV/HCV-coinfected women, liver fibrosis was an important mediator of elevations in soluble CD14 in the HCV-infected groups." (PMID 31304190, 2019). "Macrophages derived from CD14+ monocytes sourced from peripheral blood or leukapheresis can reverse experimental liver fibrosis." (PMID 28673774, 2017). "The miR-31 target, CD14 (Cluster of differentiation 14) involved in transmission and release of polysaccharides, is also implicated in ALD, hepatic cholestasis and hepatic fibrosis." (PMID 24428929, 2014). "Mac-2BP glycoprotein is a biomarker of liver fibrosis produced by Kupffer cells and CD14 is a glycoprotein that is a co-receptor for recognition of lipopolysaccharide and is shed from the surface of liver-resident and circulating activated macrophages and monocytes." (PMID 35482664, 2022). "Some of these genes have been previously implicated in liver fibrosis (Serpine133, Tgm234), while role of others (Cd14, Marco, Csf1) have not been investigated to date." (PMID 32398673, 2020). "However, according to the results of a previous study, the accumulation of CD14+HLA-DRhiCD206+ cells is positively correlated with the degree of liver fibrosis." (PMID 33050138, 2020). "A reduction in hepatic expression of CCR2, eight weeks after a CD11b CD14+ monocyte infusion, may indicate a reduction of Ly6Chi monocytes of pro-inflammatory profile in liver of the animals submitted to cell therapy, favoring the liver fibrosis improvement." (PMID 31015492, 2019). "The same trend was observed in male Gpr183–/– compared to male WT with significantly lower levels of pro-inflammatory marker Il1β, liver fibrosis markers α-SMA, Col1a1, and Mcp1, and macrophage markers Adgre1 and Cd14." (PMID 39545055, 2024).